CITED2 (Cbp/p300 interacting transactivator with ED-rich tail 2)
Description:
Transcriptional coactivator of the p300/CBP-mediated transcription complex. Acts as a bridge, linking TFAP2 transcription factors and the p300/CBP transcriptional coactivator complex in order to stimulate TFAP2-mediated transcriptional activation. Positively regulates TGF-beta signaling through its association with the SMAD/p300/CBP-mediated transcriptional coactivator complex. Stimulates the peroxisome proliferator-activated receptors PPARA transcriptional activity. Enhances estrogen-dependent transactivation mediated by estrogen receptors. Also acts as a transcriptional corepressor; interferes with the binding of the transcription factors HIF1A or STAT2 and the p300/CBP transcriptional coactivator complex. Participates in sex determination and early gonad development by stimulating transcription activation of SRY. Plays a role in controlling left-right patterning during embryogenesis; potentiates transcriptional activation of NODAL-mediated gene transcription in the left lateral plate mesoderm (LPM). Plays an essential role in differentiation of the adrenal cortex from the adrenogonadal primordium (AGP); stimulates WT1-mediated transcription activation thereby up-regulating the nuclear hormone receptor NR5A1 promoter activity. Associates with chromatin to the PITX2 P1 promoter region.
Synonyms: MRG-1; MRG1; ASD8; P35SRJ; VSD2
Tractability: No criterion of Open Targets' tractability assessment is met for any kind of drug.
Gene: Protein-coding gene on chromosome 6 (139,371,807 to 139,375,909, reverse strand). Ensembl gene ENSG00000164442.
Subcellular location: Nucleus
Subcellular location (Human Protein Atlas): Nucleoplasm; Cytosol; Golgi apparatus; Vesicles
Pathways (Reactome):
Gene expression (Transcription): Activation of the TFAP2 (AP-2) family of transcription factors; FOXO-mediated transcription of cell death genes; TFAP2 (AP-2) family regulates transcription of other transcription factors
Cellular responses to stimuli: Regulation of gene expression by Hypoxia-inducible Factor
Gene Ontology:
Molecular function: histone acetyltransferase binding; LBD domain binding; protein binding; protein domain specific binding; transcription coactivator activity; transcription corepressor activity; chromatin binding; RNA polymerase II-specific DNA-binding transcription factor binding; SMAD binding
Biological process: cell population proliferation; cellular response to hypoxia; heart development; negative regulation of cell migration; negative regulation of DNA-templated transcription; negative regulation of gene expression; negative regulation of transcription by RNA polymerase II; positive regulation of DNA-templated transcription; positive regulation of gene expression; positive regulation of peroxisome proliferator activated receptor signaling pathway; positive regulation of transcription by RNA polymerase II; response to estrogen; response to fluid shear stress; response to hypoxia; adrenal cortex formation; determination of left/right asymmetry in lateral mesoderm; determination of left/right symmetry; embryonic heart tube left/right pattern formation; left/right axis specification; left/right pattern formation; liver development; negative regulation of apoptotic process; nodal signaling pathway; outflow tract morphogenesis; positive regulation of cell cycle; and 8 more
Cellular component: nucleoplasm; nucleus; protein-containing complex; chromatin
Genetic constraint (gnomAD): Loss-of-function variants: 2 observed, 10.7 expected, observed/expected ratio (o/e) 0.19, 90% interval 0.075 to 0.59. The synonymous counts are far from expectation, so gnomAD's model fits this gene poorly and the ratio says little. Missense variants: 437 observed, 382.37 expected, observed/expected ratio (o/e) 1.14, 90% interval 1.06 to 1.24. Synonymous variants: 210 observed, 151.18 expected, observed/expected ratio (o/e) 1.39, 90% interval 1.24 to 1.56.
Gene-disease validity (ClinGen):
ClinGen rates the evidence that CITED2 causes each of these diseases.
congenital heart disease (autosomal dominant): Moderate. A heart disease that is present at birth.
Homologues: Orthologues: chimpanzee CITED2 (99% identical), macaque CITED2 (99% identical), dog CITED2 (97% identical), pig CITED2 (96% identical), rat Cited2 (95% identical), mouse Cited2 (95% identical), guinea pig CITED2 (94% identical), rabbit CITED2 (82% identical), tropical clawed frog cited2 (69% identical), zebrafish cited2 (57% identical). Paralogues in human: CITED1 (26% identical), CITED4 (19% identical).
Diseases named in the same sentence as CITED2 in open-access papers:
CITED2 is named in the same sentence as 88 diseases in open-access papers, as found by Europe PMC text mining. Sharing a sentence is not in itself a finding about the gene and the disease. The quoted sentences say what the papers report.
breast carcinoma (16 papers, 2009 to 2025). "For example, studies have shown that amplification of the CITED2 gene is associated with increased expression in certain types of cancer, including breast cancer and metastatic prostate cancer." (PMID 39907030, 2025). "Importantly, our experiments have shown that NCOR2, CITED2 and other genes previously revealed through functional screening are implicated in breast cancer outcome and therefore bear clinical relevance." (PMID 19904269, 2009). "The associations of NCOR2 and CITED2 with outcome in oestrogen receptor-positive breast cancer patients underscore the clinical relevance of functional genetic screens to better understand disease progression, which may ultimately lead to the development of improved treatment options." (PMID 19904269, 2009). "In addition to its association with tumour aggressiveness, high levels of CITED2 mRNA were also significantly associated with clinical benefit of tamoxifen treatment in advanced breast cancer independently of the traditional predictive markers including adjuvant chemotherapy." (PMID 19904269, 2009). "From this analysis, we identified genes such as CITED2 and DUSP6 that are previously implicated in breast cancer metastasis." (PMID 37117180, 2023). "Transcriptional co-regulator CITED2 has recently been reported as a prognostic factor in breast cancer patients with important roles in cancer progression, chemoresistance and metastasis." (PMID 32155786, 2020). "Correspondingly, we demonstrate that CITED2 regulates VEGFA expression in breast cancer cells, at least in part via modulation of TGF-β-induced transcription." (PMID 28008154, 2017). "We previously reported that CITED2 mRNA and protein expression was significantly elevated in primary breast tumors of breast cancer patients relative to normal mammary epithelium, with CITED2 levels being inversely correlated with patient survival." (PMID 28008154, 2017). "To address this issue, we examined the effect of CITED2 silencing on the growth of human breast cancer cell lines MDA-MB-231 and MDA-MB-468 following orthotopic administration in vivo." (PMID 28008154, 2017). "Utilizing two murine orthotopic models of human breast cancer, we provide evidence that CITED2 regulates primary tumor growth, likely secondary to effects on the formation of tumor vasculature." (PMID 28008154, 2017). "Extending this work to breast cancer in humans, we found that CITED2 expression in primary tumor and metastatic tissues was elevated relative to normal mammary epithelium, with CITED2 levels in primary tumors inversely correlating with patient survival." (PMID 28008154, 2017). "To fill this knowledge gap, we investigated the role of CITED2 in the establishment and progression of breast cancer at the primary site." (PMID 28008154, 2017). "Collectively, these data provide the first evidence of a role for CITED2 in primary breast cancer progression and a potential mechanism for its action." (PMID 28008154, 2017). "Since the MDA-MB-231 and MDA-MB-468 cell lines are both representative of the basal subtype of breast cancer, it will be interesting to examine the pro-tumorigenic and pro-metastatic effects of CITED2 in other breast cancer subtypes." (PMID 28008154, 2017). "The ability of CITED2 to influence both primary breast cancer growth and metastatic progression in model systems, underscores its potential importance as a tumor-promoting factor." (PMID 28008154, 2017). "In previous studies, we identified CITED2 as being over-expressed in primary human breast cancers relative to normal mammary epithelium, negatively correlating with survival." (PMID 28008154, 2017). "To explore the functional impact of CITED2 in primary breast cancer, we utilized the human MDA-MB-231 and MDA-MB-468 breast cancer cell lines." (PMID 28008154, 2017). "In initial studies, we identified the ability of CITED2 to facilitate bone metastasis in a murine mammary cancer model." (PMID 28008154, 2017).
breast carcinoma (continued). "Our results have shown the expressional association and clinical relevance of six genes (CDH2, FN1, CITED2, CTNNB1, and CTNNA3) together with GRHL2 for breast cancer metastases." (PMID 23441166, 2013). "CITED2 downregulation impacted pathways, including breast cancer, MAPK, and IL-17." (PMID 40313859, 2025). "TGF-β1 could negatively regulate Cited2 in breast cancer cells, epithelial cells, and leiomyoma cells, and TGF-β1 expression is up-regulated in hypoxia, which is related to pulmonary vascular remodeling and the PH development." (PMID 38419888, 2024). "In breast cancer, researchers indicated that CITED2, as a transcriptional coactivator, could modulate the metastatic ability of tumor cells through the regulation on IKKα." (PMID 37730669, 2023). "However, mounting evidence suggests a potential role of CITED2 in the development and progression of several human malignancies, including breast cancer." (PMID 34569432, 2021). "This suggests that CITED2 expression could be a predictive biomarker of response to THZ1 in breast cancer." (PMID 32155786, 2020). "CITED2 promotes proliferation, migration and resistance to chemotherapy in breast cancer." (PMID 32155786, 2020). "Similarly, we chose RHOA, MKI67, CITED2, ACTA2, FN1 and TGFB3, as all have been implicated in EMT and highly metastatic breast cancer." (PMID 23441166, 2013). "As viral integrations in both NCOR2 and CITED2 yielded differences in gene expression patterns in our cell model, we quantified their mRNA levels in breast cancer tissues to further investigate the role of these two genes in tumour aggressiveness and resistance to tamoxifen." (PMID 19904269, 2009). "In fibroblasts, similar to breast cancer cells, FOXO3a inhibited HIF1-induced apoptosis via CITED2, resulting in reduced expression of NAP1 and RTP801 (pro-apoptotic)." (PMID 38636197, 2024). "Knockdown of ELK-1, a member of the Ets family of transcription factors, significantly reduced hypoxic induction of the HIF-2α target genes, including CITED2, WISP2, and IGFBP3 in MCF-7 breast cancer cells." (PMID 30478339, 2018). "Training on public gene expression profiles of 995 breast cancer patients, this method prioritized one gene-set pair (GRHL2, CDH2, FN1, CITED2, MKI67 versus CTNNB1 and CTNNA3) from all 2717 possible gene-set pairs (GSPs)." (PMID 23441166, 2013). "Preliminary analyses in a subset of 120 patients for whom the molecular breast cancer subtype was known suggest that NCOR2 and CITED2 mRNA levels are particularly prognostic in patients with luminal A tumours, but not luminal B tumours (data not shown)." (PMID 19904269, 2009). "According to previous studies, CITED2 regulates the expression of several growth factors such as transforming growth factor-beta (TGFβ), interleukin 11 (IL-11), interleukin 1 beta (IL-1β) and HIF-1α to promote breast cancer progression." (PMID 34569432, 2021). "In thyroid, ovarian, lung, and breast cancers, CITED2 expression was not correlated with overall survival." (PMID 30291252, 2018). "Here, we have shown that silencing of the non-DNA binding transcriptional co-regulator CITED2 significantly attenuates the growth of human breast cancer in an orthotopic tumor model, likely secondary to effects on tumor vascularization." (PMID 28008154, 2017). "However, Cited2 could also modulate TGF-β-mediated up-regulation of VEGFA and MMP9 in human breast cancer cell lines." (PMID 38419888, 2024). "Furthermore, basal protein expression of one of these genes, CITED2, correlated with THZ1 sensitivity, suggesting that CITED2 may serve as a possible biomarker of response to CDK7 inhibitors in the treatment of all breast cancer subtypes." (PMID 32155786, 2020).
breast carcinoma (continued). "Suntag-KRAB repression at the CITED2 enhancers confirms that CI54 most significantly affects transcription, while Cas9-mediated CI54 deletion in the CITED2 expressing AR+ breast cancer cell line MDA-MB453 did not result in a transcriptional decrease, as this cell line does not use enhancer CI54." (PMID 36450752, 2022).
congenital heart disease (13 papers, 2009 to 2026). "In that context, it seems relevant that loss of Cited2 in mouse causes congenital heart disease by perturbing left-right patterning of the body axis." (PMID 32475352, 2020). "Mutations and inadequate methylation profiles of CITED2 are associated with human congenital heart disease (CHD)." (PMID 31378782, 2019). "To explore the potential impact of mutations in CITED2 on congenital heart disease (CHD) in humans, we screened the coding region of CITED2 in a total of 700 Chinese people with congenital heart disease and 250 healthy individuals as controls." (PMID 24848765, 2014). "In this study, we have investigated the role of CITED2 gene mutation and methylation in the development of Congenital Heart Disease in pediatric patients in China." (PMID 24456003, 2014). "In conclusion, we demonstrated that CITED2 has a potential causative impact on congenital heart disease." (PMID 24848765, 2014). "Our resequencing study reported here and those reported elsewhere indicate that non-synonymous mutations of CITED2 can be observed in patients with congenital heart disease, and that these mutations tend to cluster in the SRJ domain." (PMID 23082118, 2012). "CITED2 mutations are found in patients with congenital heart disease, lending clinical significance in trying to understand CITED2 function." (PMID 19951693, 2009). "In humans, CITED2 variants are associated with congenital heart disease." (PMID 41827883, 2026). "Our study suggests that CITED2 gene mutations and methylation may play an important role in the development of pediatric congenital heart disease." (PMID 24456003, 2014). "CITED2 variants were found in children with congenital heart disease (CHD), which was the first evidence to prove that CITED2 is the pathogenic gene for human congenital heart malformations." (PMID 36358994, 2022). "A close correlation has been discovered between congenital heart disease with the CITED2 gene deletion and environmental alteration." (PMID 24456003, 2014). "Notably, CITED2 loss of function is strongly associated with congenital heart malformations in mice and zebrafish embryos, as well as congenital heart disease (CHD) in humans, whereas other CITED family members are not critical for cardiogenesis." (PMID 41295244, 2025). "On the other hand, it seems that the role of genes, such as GATA4, TBX5, NKX2-5, HOMEZ, PLAGL1, and CITED2, in heart development is significant, as numerous studies on knockout mice report that mutations in these genes are frequently associated with VSD or other congenital heart anomalies." (PMID 39466144, 2025).
gastric cancer (7 papers, 2013 to 2025). A primary or metastatic malignant neoplasm involving the stomach. "In addition, miR-153 regulates drug resistance by modulating expression of Cbp/p300-interacting transactivator 2 (CITED2), which is implicated in drug resistance of gastric cancer cells." (PMID 36158686, 2022). "A study has shown that the pan-histone deacetylase inhibitor panobinostat sensitizes gastric cancer cells to anthracyclines via the induction of CITED2." (PMID 33902514, 2021). "Expressions of hsa-miR-153-3p/CITED2 were also assessed in FGD5-AS1-downregulated gastric cancer cells." (PMID 32849774, 2020). "We demonstrated that FGD5-AS1 can regulate human gastric cancer cell functions, possibly through its downstream epigenetic axis of hsa-miR-153-3p/CITED2." (PMID 32849774, 2020). "Hsa-miR-153-3p was knocked down and CITED2 was upregulated to assess their direct functional correlations with FGD5-AS1 in gastric cancer." (PMID 32849774, 2020). "After that, qRT-PCR indicated that CITED2 expression was markedly upregulated by pc/CITED2 transfection in gastric cancer cell lines (*P < 0.05)." (PMID 32849774, 2020). "Hsa-miR-153-3p inhibition or CITED2 upregulation reversed the tumor-suppressing effects of FGD5-AS1 downregulation on gastric cancer proliferation and 5-FU chemoresistance." (PMID 32849774, 2020). "Panobinostat, when used in combination with anthracyclines, works as a chemosensitizing agent for gastric cancer cells via activation of CITED2 (Cbp/p300-interacting transactivator 2)." (PMID 31244652, 2019). "Histone acetylation promotes CITED2 expression in gastric cancer cells." (PMID 39907030, 2025). "In addition, we revealed that the epigenetic axis of hsa-miR-153-3p/CITED2 is directly correlated with FGD5-AS1 in regulating gastric cancer cell proliferation and 5-FU chemoresistance." (PMID 32849774, 2020). "Hsa-miR-153-3p/CITED2 axis was confirmed to be downstream of FGD5-AS1 in gastric cancer." (PMID 32849774, 2020). "In addition, qRT-PCR showed that hsa-miR-153-3p expression was upregulated, whereas CITED2 was downregulated by FGD5-AS1 downregulation in gastric cancer cells." (PMID 32849774, 2020). "Additionally, in this study, we identified an epigenetic axis of hsa-miR-153-3p/CITED2 to be the downstream ceRNA candidate of FGD5-AS1 in gastric cancer." (PMID 32849774, 2020). "In addition, resistance to chemotherapy may be mediated by Lnc-RNA FGD5-AS1 suppressing miR-153 and upregulating CITED2, a gene target of miR-153, in gastric cancer." (PMID 36158686, 2022). "Most importantly, through further genetic engineering approaches, we demonstrated that miR-153-3p downregulation or CITED2 upregulation could directly reverse the inhibitory effect of FGD5-AS1 downregulation on gastric cancer proliferation and 5-FU chemoresistance." (PMID 32849774, 2020). "CITED2 knockdown in cell lines with high CITED2 expression led to a decrease of their proliferation, mitochondrial membrane potential, colony formation, and an induced cell cycle arrest and apoptosis in MKN74 gastric cancer cell line." (PMID 39907030, 2025).